IL6 (interleukin 6)
Diseases named in the same sentence as IL6 in open-access papers (continued):
Sharing a sentence is not in itself a finding about the gene and the disease.
tumor (continued). "It is reported that long-term radiation induces upregulation of IL-6 and IL-8 in tumor cells and treatment with temozolomide increases production of inflammatory mediators in brain." (PMID 28891967, 2017). "Interleukin-6 (IL-6), a pro-inflammatory cytokine produced by several types of immune cells and carcinomas, is an important mediator of the tumor-promoting effects of inflammation, especially in later states of tumorigenesis." (PMID 28388577, 2017). "TAMs generally resemble functional features typical of the M2 anti-inflammatory phenotype; nonetheless, they can also secrete pro-inflammatory cytokines, such as IL-6, that are involved in oncogenic programmes during tumour development." (PMID 28404796, 2017). "We also noted remarkably elevated iNOS and NO production and decreased tumor growth-associated cytokines such as IL-10, TGF-β, IL-6, and VEGF in tumor tissues of recipient animals." (PMID 28243242, 2017). "It had confirmed that IL-6 contributes to poor therapeutic effect, tumor recurrence and aggressive tumor growth." (PMID 29296206, 2017). "For example, IL6 was found to be upregulated both in the tumor buds and in the microenvironment and to be located in the interactive-regulatory signaling network of EMT." (PMID 28687755, 2017). "Among their effects, neutrophils together with tumor cells promoted an IL-6 and IL-8 rich environment." (PMID 28827632, 2017). "IL-17A and IL-23 cause the attraction of lamina propria myeloid cells (macrophages, granulocytes) to the tumor site which are the major source of IL-6 and TNF." (PMID 28881611, 2017). "In this longitudinal study, the first blood samples were collected from those patients who underwent tumor resection and both serum Shh and IL-6 levels were analyzed." (PMID 28496132, 2017). "IL-6 promotes tumor proliferation, IL-8 leads to neovascularization, growth, angiogenesis and metastasis, and TNFα affects necrosis, invasion and metastasis." (PMID 28832545, 2017). "We then analyzed the Shh and IL-6 concentrations in cell supernatants from freshly harvested tumor cells from patients." (PMID 28496132, 2017). "In this model, Nur77 knockout mice not only developed more severe hepatic fibrosis with elevated circulating IL-6 but also generated twice as many as tumour numbers and over four times larger tumours than WT mice." (PMID 28240261, 2017). "IL-6 has been reported to promote tumor-cell survival, and a higher level of IL-6 was significantly associated with an unfavorable prognosis in cancer patients." (PMID 29262550, 2017). "The levels of related cytokines (IL-6, IL-10 and IL-12) were also detected by ELISA using the homogenate of tumor tissues." (PMID 29383114, 2017). "M1 macrophages express high levels of pro-inflammatory cytokines (TNF-α, IL-6, and IL-12) and are capable of killing pathogens and priming anti-tumor immune responses." (PMID 29245934, 2017). "STAT3 activation induces IL-6 expression in both tumor and stromal cells and creates a tumor-promoting inflammatory microenvironment." (PMID 28725043, 2017). "These processes are thought to be highly dependent on interleukin-6 (IL-6), as targeting IL-6/IL-6 receptor (IL-6R) signaling decreases PCM tumor growth in vitro and in vivo." (PMID 27661006, 2017). "IL-6 induces MDSCs generation, and inhibition of IL-6 abrogates generation of MDSCs in tumor-bearing mice." (PMID 29326716, 2017). "Our previous study showed that G-CSF and IL-6 can induce the conversion of neutrophil function from tumor-suppressing to tumor-promoting." (PMID 28432279, 2017). "It is well known that pro-tumorigenic microenvironment inflammatory factors (such as IL-6, IL-1β) can promote tumor progression and remarkably impede therapy responses." (PMID 28881683, 2017). "The tumor infiltrating CD11b+CCR8+ myeloid subset produced significant amount of proinflammatory IL-6 and angiogenic VEGF and induced the differentiation of CD4+FoxP3+ regulatory T-cells." (PMID 28197019, 2017).
tumor (continued). "IDO and IL-6 incorporate a positive feedback signal loop to maintain IDO and IL-6 constitutive expression and facilitate tumor progression." (PMID 29296206, 2017). "Our results in vivo showed that IL-6 significantly promote tumor growth in vivo compared with HCC with HCCLM3-IL6(-) cells (7659.0±215.4 mm3 versus 5567.4±254.4 mm3, P=.013)." (PMID 29100435, 2017). "Macrophages contribute to cancer-related inflammation and sequential production of cytokines such as IL-6 and TNF-α which cause various biological processes that promote tumor initiation, growth and metastasis." (PMID 28969049, 2017). "IL-6 is a potent inflammatory cytokine involved in tumor inflammation, epithelial to mesenchymal transition (EMT) and tumor progression." (PMID 28416734, 2017). "This work indicates that LMP1-mediated glycolysis regulates IL-1β, IL-6 and GM-CSF production through the NLRP3 inflammasome, COX-2 and P-p65 signaling pathways to enhance tumor-associated MDSC expansion, which leads to tumor immunosuppression in NPC." (PMID 28732079, 2017). "IL-6 and IL-10 belong to T-helper type 2 cell cytokines, contributing to inhibition of host's immune system and induction of tumor progression." (PMID 29109622, 2017). "IL-6 released by senescent cells can be sustained and enhanced in autocrine manner while IL-6 promotes the proliferation of surrounding tumor cells in paracrine manner." (PMID 28360909, 2017). "In clinic, IL-6-mediated STAT3 abnormal activation predicts tumor progression and poor prognosis in breast, lung, and hematopoietic tumors with gp130 constitutive activation or elevated IL-6 levels." (PMID 27861147, 2017). "Dysregulated IL6 production has been identified in several cancers, often positively correlated with tumor growth and invasive behaviors." (PMID 29250030, 2017). "To mimic an AFG1-induced tumor-associated inflammatory microenvironment in vitro, we treated A549 cells and human macrophage THP-1 (MΦ-THP-1) cells with AFG1, TNF-α and/or IL-6 respectively." (PMID 28801561, 2017). "Platelets can accumulate following the stimulation of megakaryocytes by inflammatory mediators that are released by the tumor or its microenvironment, such as interleukin (IL)-1, IL-3 and IL-6." (PMID 28489884, 2017). "The SASP has recently been shown contribute to multiple biological functions such as tumor suppression, tissue repair, and aging, through either the autocrine or paracrine mechanisms of various secretory factors including IL6 and IL8." (PMID 28691365, 2017). "For further determine the role of IL-6 in vivo, tumor-bearing mice were treated with intraperitoneally injection of IL-6 (1 mg per mice) at 1, 2 and 3 weeks after LLC inoculation." (PMID 29383114, 2017). "Cancer-associated fibroblasts (CAFs) have been identified as a key source of interleukin 6 (IL-6), which signals tumor inflammatory and immune responses, tumor proliferation, and tumor angiogenesis." (PMID 28825637, 2017). "The implication of IL-6 in the pathogenesis of EOC is well-documented: it seems the primary source of IL-6 secreted in biological fluids is produced by the tumor tissue." (PMID 28848618, 2017). "During the early stages of tumor development, TAMs seem to acquire a classical activated M1 phenotype secreting proinflammatory mediators, such as IL-1, IL-6, TNFα, IL-23, and iNOS, which are involved in tumor initiation." (PMID 28769537, 2017). "Another study found that nude mice treated with 250 mg/kg/day metformin two days before inoculation with HCC827-pSB388 cells showed decreased tumor growth, reversed IL-6 induced EMT and blocked STAT3 phosphorylation." (PMID 28481268, 2017). "Authors have shown localized expression of IL-6 in tumor cells, macrophages, and ischemic necrosis by using immunohistochemistry (IHC) staining." (PMID 28346397, 2017). "Independent studies showed that tumor cells acquire metastatic potential through IL-6/STAT3 pathway." (PMID 29245982, 2017).
tumor (continued). "Together, these results indicated that the RAB3C protein plays a critical role in tumor progression, invasion, and metastasis through IL-6 exocytosis." (PMID 28784136, 2017). "Local signals in the tumor microenvironment (IL-4, IL-6, IL-10, PGE2, CSF-1, and transforming growth factor-β, TGF-β) polarize macrophages into alternative, protumoral M2-like cells." (PMID 28197019, 2017). "Macrophages and some of their products (IL-1, TNF, IL-6, and IL-18) are also known to increase the likelihood of metastasis while creating appropriate microenvironmental niches for preserving tumor cells." (PMID 28487844, 2017). "C-reactive protein levels, hemoglobin levels, and tumor grade were strongly correlated with IL-6 levels." (PMID 28851899, 2017). "IL-6 has been reported to induce tumor progression, especially metastasis, in various cancer types and is also considered to be a potential therapeutic target." (PMID 28784136, 2017). "In tumors, tumor cells can produce a soluble form of IL‐6Rα which binds to IL‐6, enabling the so‐formed dimer to interact with gp130 at the surface of cancer cells and initiate prosurvival signaling." (PMID 28599100, 2017). "IL-6 contributes to tumor metastasis via the JAK/Stat3 signaling pathway, and IL-10 phosphorylates of Stat3 in PCNSL cells, while the role of IL-6 in PCNSL remains poorly defined." (PMID 28415725, 2017). "First, neutrophils, as a type of inflammatory cells, are involved in different steps of tumor development through the production of a variety of cytokines, such as oncostatin M, interleukin-6, hepatocyte growth factor, and tumor necrosis factor." (PMID 29029493, 2017). "Two of the most important downstream factors of NF-κB shown to be important for tumor growth are pro-inflammatory, pro-angiogenic factors IL6 and IL839,40,41." (PMID 28337983, 2017). "The prominence of IL-6 suggests that IL-6 plays a role in BC progression and tumor growth, and therefore based on these results, we restricted our analysis to IL-6 and possible association with Shh19." (PMID 28496132, 2017). "In this context, proliferation of tumor-initiating cells is enhanced by IL-6 while normal and premalignant intestinal epithelial cells are protected from apoptosis." (PMID 28938014, 2017). "The IL-6/IL-6R/STAT3 pathway mediates interactions between tumor cells and the TME and contributes to the development of drug resistance." (PMID 28928376, 2017). "We have identified Dub3 as the key regulator of Snail and the missing link between extracellular signaling from sources such as IL-6 in tumor environment, and the gene expression changes in cells that promote cancer." (PMID 29147673, 2017). "Tumor epithelial cell-derived cytokines, including IL-6 and TNFα, induce CAF activation or desmoplasia, characterised by SMA expression." (PMID 28416734, 2017). "Long-term culture of human MSCs for 12–16 days in conditioned medium taken from ovarian cancer cell line, SKOV-3, induced the expression of CAF markers in MSCs and elevated secretion of IL-6, leading to increased tumour cell proliferation." (PMID 28148268, 2017). "Parallel IL-6 expression results (P < 0.05) were confirmed by ELISA in the tumor homogenate supernatants." (PMID 28243242, 2017). "Active IL-1β and IL-18 can regulate the differentiation of tumor and T helper (Th) cells through downstream signal molecules including NFκB and IL-6." (PMID 29312552, 2017). "We then detected the expression of IL-6 inflammatory factors in tumor specimens of 4T1 and lung specimens of MDA-MB-231." (PMID 28088791, 2017). "After treatment period, cytokines, Interleukin 2, IL-6, IL-7, IL-10, IL-15, 1 L-17 and TNFα in CT-26 tumor bearing BALB/c mice serum were analysed." (PMID 29246138, 2017). "Another important inflammatory cell type, tumor-associated macrophages, also promote tumor progression and metastasis by producing cytokines such as TNF-α, IL-1, IL-6, and transforming growth factor beta (TGF-β)." (PMID 28737711, 2017).
tumor (continued). "In preclinical mouse models genetic evidence has been provided that cytokines produced by the pro-inflammatory T helper cell subsets Th1 and Th17, in particular tumor necrosis factor (TNF), IL-6, IL-23 and IL-17, promote tumor growth and survival." (PMID 28881611, 2017). "Although its precise role is still under debate, IL-6 released by osteoclasts seems to increase MM tumor burden, and enhance bone destruction since it increases production of IL-17 by T-cells." (PMID 28099912, 2017). "As a consequence, an impaired recruitment and activity of tumor-infiltrating leukocytes resulting in decreased secretion of cytokines IL-6 and TNF-α was observed." (PMID 28881574, 2017). "We have recently shown that overexpression of IL-6 in CAL27 cells (CAL27-IL-6) significantly enhances tumor growth and tumor metastasis." (PMID 28978005, 2017). "KSHV-infected monocytes produce a general proinflammatory response similar to the KS tumor microenvironment cytokines with enrichment of IL-1α, IL-1β, and IL-6 compared to uninfected control cells." (PMID 29018115, 2017). "A logistic regression model confirmed that tumor size (OR: 1.17, p = 0.003) and IL-6 level (OR: 1.05, p = 0004) remained significant predictors of STS diagnosis." (PMID 28851899, 2017). "Interleukin-6 (IL-6) is a cytokine present in tumor microenvironment and can promote EMT through enhancing STAT3, MAPK and Akt signaling." (PMID 29088764, 2017). "Emerging evidence indicates that tumor-promoting macrophages support cancer stem cell renewal, maintenance, and migratory capacity through the secretion of numerous factors including IL-6 and TNFα." (PMID 28881599, 2017). "Tumor development was associated with the appearance of F4/80+CD11bhighGr1low M2 macrophages that produced the tumor-promoting factors IL-6 and EGF, in a CD1d- and IL-13-dependent manner." (PMID 29375569, 2017). "We found that tumor grade was also a prognostic factor for survival and oncological events in addition to IL-6." (PMID 28851899, 2017). "Clusters of CD8+ T lymphocytes were observed at the periphery of small residual tumor masses in the peritoneal cavity, which presented a significant reduction in mitotic index, IL6 and vimentin expression compared with tumors in untreated rats." (PMID 28915695, 2017). "Recent publications have identified the importance of IL-6 in the regulation of Shh secretion in the tumor microenvironment." (PMID 28496132, 2017). "In this study, RERG decreased IL8, IL6 and IL1β expression and angiogenesis in tumor xenografts in nude mice." (PMID 28659184, 2017). "IL6 is a pro‐proliferative cytokine, which promotes tumor growth and is enhanced after CHM1 suppression in ES cells." (PMID 28319320, 2017). "Accompanied downregulating of pro-inflammatory cytokines such as IL-6 contributes to inhibition of tumor growth by proteasome inhibitors." (PMID 28881611, 2017). "We observed completely healthy livers free of tumours when FGF19-expressing Mdr2−/−mice were treated with anti-IL-6, whereas those treated with isotype control antibodies develop HCC." (PMID 28508871, 2017). "YAP1-silencing led to the concomitant decreased expression of major oncogenic pathways including Kras, mTOR, β-catenin, and M2-promoting IL-4 and tumor-promoting IL-6 cytokines." (PMID 28241877, 2017). "One significant finding suggests that IL-6 secreted from tumor cells promotes tumorigenesis, angiogenesis, and metastasis." (PMID 29296192, 2017). "An aberrant IL-6/STAT3/lncTCF7 signaling axis, in which IL-6 in tumor microenvironment induces lncTCF7 via activating STAT3, contributes to hapatocellular carcinoma cells aggressiveness through EMT induction." (PMID 27992370, 2017). "In a tumor microenvironment, IL-6 is one of the major cytokines that can be secreted by tumor and stromal cells." (PMID 28208810, 2017).
tumor (continued). "Another pathway is related to genetic changes, which induce reconstruction of tumor microenvironment, resulting in expression of pro-tumorigenic factors involving IL-6, IL-8, VEGF, or MMP9." (PMID 28212583, 2017). "The tumor microenvironment is a complex system, including various kinds of cells, e.g., tumor cells, immune cells, etc., and cytokines, e.g., IL-6, IL-10, TGF-β, etc.." (PMID 28234961, 2017). "Recently, tumor stromal cells were reported to promote cancer cells to gain CSC properties through production of IL-6 or TGF-β1-induced EMT." (PMID 29245907, 2017). "Mechanisms of CAF-tumor cell interaction have been described including exosomal transfer and paracrine signaling mediated by cytokines such as GM-CSF and IL-6." (PMID 28351381, 2017). "RT further affects the tumor microenvironment by inducing increased expression of pro-inflammatory cytokines, such as TNF-α, IFN-γ, IL-1β, IL-6 and IL-12, type-I interferons and chemokines, which stimulate infiltration of immune cells into the tumor." (PMID 28233730, 2017). "Our previous studies suggested that IL-6 was proven to be an important factor in tumor growth and metastasis." (PMID 29100435, 2017). "Previous literatures indicated that IL-6 is involved in facilitation of tumor growth via regulating all hallmarks of cancer and multiple signaling pathways." (PMID 28243242, 2017). "In summary, these results indicate that IL-6 produced in the liver microenvironment is important for tumour development initiated by FGF19." (PMID 28508871, 2017). "This raises the possibilities of utilizing Shh inhibitors to overcome IL-6 induced tumor progression." (PMID 28496132, 2017). "IL-6, a major cytokine present in the tumor microenvironment, can induce EMT and promote metastasis through the STAT3 signaling pathway in breast cancer, head and neck cancer and pancreatic cancer." (PMID 29147673, 2017). "Using the Eμ-myc model of Burkitt’s lymphoma, Gilbert and Hemann showed that doxorubicin induced a senescence response in the thymic stroma accompanied by an acute increase in thymic IL-6 levels in non-tumor-bearing mice and lymphoma-bearing mice." (PMID 29263785, 2017). "We found that more MDSCs infiltrated IL-6 high-expressing cancer tissues, and that tumor-derived IL-6 displayed a strong positive correlation with the number of infiltrating MDSCs in situ at both the mRNA and protein levels." (PMID 29326716, 2017). "It has been shown that anti-tumor immunity is suppressed by inflammatory factor IL-6 by decreasing ketogenesis." (PMID 28931870, 2017). "Our findings suggested that the tumor suppressive effect of GMI was via inhibition of IL-6/Stat3 signaling." (PMID 29050290, 2017). "CAFs release interleukins, such as interleukin-6 (IL-6) which promote tumor cells survival and growth." (PMID 29383119, 2017). "For example, CCL2 and IL-6 were found to contribute to the survival of CD11b+ myeloid monocytes recruited to the tumor microenvironment and skew the phenotype toward tumor-promoting CD14+/CD206+ M2-type macrophages." (PMID 28948005, 2017). "Tumour-promoting cytokines IL6 and Tnfα,23 multipotency transcription factors Sox2, Oct4 and Nanog24 and oncogenic factors c-myc and Ras25 were all upregulated in invaded host cells." (PMID 28300841, 2017). "IL-6, IL-1β, and LCN2, previously associated with tumor growth and metastasis, were up-regulated in LuM cells." (PMID 28410227, 2017). "Release of IFN-γ and IL-6 was also confirmed on the protein level using a model of ex vivo cultured tumour explants." (PMID 28300057, 2017). "In PDAC microenvironment, IL-6 is one of the most abundant proinflammatory cytokines secreted by PSCs and tumor cells." (PMID 29254283, 2017). "Our results show that L-4F treatment significantly inhibited tumor progression, decreased inflammatory cell infiltration in tumor tissues, and reduced percentages of IL-17A-, IL-6-, GM-CSF- and IL-1β-producing cells to varying degrees in tumor tissues." (PMID 29245934, 2017).